ZEB1 (zinc finger E-box binding homeobox 1)
Diseases named in the same sentence as ZEB1 in open-access papers (continued):
Sharing a sentence is not in itself a finding about the gene and the disease.
lung carcinoma (continued). "In this study, we tested the hypothesis that naringin has anticancer actions through inhibition of Zeb1, a zinc finger homeodomain transcription factor implicated in invasiveness and metastasis development in several tumor types, including osteosarcoma and lung cancer." (PMID 30580326, 2018). "Zinc finger E-box-binding homeobox 1 (ZEB1) bound to the FBP1 promoter to enhance DNA methylation in lung cancer." (PMID 29556139, 2018). "It will be interesting to determine if TLE1 functions independently from or synergistically with CtBP to effect full ZEB1-dependent repression of E-cadherin in lung cancer cells." (PMID 29069783, 2017). "Given that ZEB1 has been shown to be the key transcription factor in repressing E-cadherin expression in lung cancer cells, we then examined if ZEB1 functions as the DNA-binding transcription factor mediating the observed TLE1-mediated E-cadherin repression." (PMID 29069783, 2017). "We reported a global decrease in H3K27 acetylation in a ZEB1-induced EMT lung cancer cell model and suggested that ZEB1 would recruit EZH2." (PMID 28804523, 2017). "In lung cancer specifically, Chen and colleagues have shown that PD-L1 expression is regulated by the miR-200/ZEB1 loop, and suggest that increased expression of ZEB1 in mesenchymal cell lines prompt increased expression of PD-L1." (PMID 28978110, 2017). "In summary, the findings presented here have identified the ZEB1/TLE1 as a new transcriptional mechanism in the suppression of E-cadherin in lung cancer cells." (PMID 29069783, 2017). "These collective results suggest that TLE1 is an effector of anchorage-independent growth of lung cancer cells, at least in part, through the transcription factor ZEB1." (PMID 29069783, 2017). "Direct transcriptional suppression of E-cadherin expression by TLE1 via the transcription factor ZEB1 conferred enhanced anoikis insensitivity, anchorage-independent growth in vitro, and tumorigenicity in vivo of lung cancer cells." (PMID 29069783, 2017). "The Zinc-finger E-box-binding Homeobox-1 (ZEB1) is a transcription factor that promotes epithelial–mesenchymal transition (EMT) and acts as an oncogene in KRAS-mutated lung cancer models." (PMID 27456471, 2016). "Here we report the mechanisms of the p66Shc-maintained epithelial phenotype and demonstrate that depletion of p66Shc induces fibrotic EMT response through ZEB1 activation in lung cancer cells." (PMID 25837484, 2015). "We present evidence correlating expression of Ets1 and Zeb1 in invasive lung adenocarcinoma, suggesting that this amplification loop is evident in invasive lung cancer." (PMID 25880398, 2015). "ZEB1, a transcription suppressor of miR-200, enhanced Bmp4 expression in a low metastatic lung cancer cell line (393P), but miR-200 suppressed Bmp4 expression in 344SQ and 531LN2, which was confirmed by Western blotting." (PMID 26395571, 2015). "We also detected the expression and sub-cellular localization of ZEB-1 because a recent study suggested that ZEB-1 plays a role in lung cancer invasiveness and metastasis development." (PMID 26177797, 2015). "In summary, we have demonstrated that p66Shc-maintained epithelial phenotype and demonstrate that p66Shc depletion induces fibrotic EMT response through ZEB1 activation in lung cancer cells." (PMID 25837484, 2015). "As already mentioned, ZEB1 was similarly shown to abrogate latent EGFR-induced senescence in lung carcinoma cells." (PMID 25566496, 2014). "Altogether, our results reveal that GLUT3 is a transcriptional target of ZEB1 and that this glucose transporter plays an important role in lung cancer, when tumor cells loose their epithelial characteristics to become more invasive." (PMID 25097756, 2014).
lung carcinoma (continued). "In the future, it will be important to decipher all of the genes that are directly targeted—either repressed or induced—by ZEB1 in lung cancer and to determine if this includes additional genes that regulate tumor cell metabolism." (PMID 25097756, 2014). "From our previous identification of ZEB1-correlated genes in lung cancer using Affymetrix arrays, we had confirmed regulatory relationships for ST14, EpCAM, and ESRP1 upon ZEB1 gain- and loss-of-function." (PMID 24216980, 2013). "Our results represent a step towards identifying the chain of events leading to changes in gene expression mediated by ZEB1 during the EMT process in lung cancer." (PMID 24216980, 2013). "The overexpression of ZEB1 was also found to promote the invasion and metastasis of lung cancer cells." (PMID 23420790, 2013). "ZEB1, an E-box binding transcription factor, is a major suppressor of epithelial genes in lung cancer." (PMID 24216980, 2013). "COX-2-dependent pathways upregulate ZEB1 and Snail, transcriptional suppressors of E-cadherin in lung cancer cells." (PMID 19568234, 2009). "Consequently, high expression of Snail, Twist1, and ZEB1 in conjunction with low expression of Smad7 and nuclear ProT was correlated with a poor prognosis in patients with lung cancer." (PMID 40259641, 2025). "Furthermore, ZEB1 promotes the invasive behavior of lung cancer by stabilizing and depositing collagen mediated by LOXL2 in the extracellular matrix." (PMID 41252548, 2025). "circ_0027446 facilitates the spreading and EMT of lung cancer via the miR-1236-3p/ZEB1 pathway." (PMID 40429981, 2025). "Furthermore, to better understand the relationship between PD-L1, EMT potential, and the miR-200/ZEB1 axis, their expression was studied in lung cancer cell lines." (PMID 39343796, 2024). "Here, we speculated that FBXO11 might have a similar regulatory effect on ZEB1 in lung cancer cells." (PMID 39409891, 2024). "It was found that while PD-L1 expression was elevated in quasi-epithelial cells (murine 393P and human HCC827) with persistent ZEB1 expression, it was elevated in mesenchymal lung cancer cell lines (human H157, H1155, H1299, and H460; murine 344SQ, 531LN2, and 393P ZEB1)." (PMID 39343796, 2024). "Furthermore, prior investigations have demonstrated the co-enrichment of CD73 and ZEB1 gene expressions in lung cancer cell lines and tumors." (PMID 38388432, 2024). "In addition, the positive correlation of CIB2 and ZEB1 in lung cancer samples was analyzed with the GEPIA database." (PMID 39264588, 2024). "In addition, transcription factor ZEB1 was upregulated in RAECs, and elevated ZEB1 expression in ECs promotes angiogenesis, growth, and metastasis of lung cancer cells by increasing TGF-β levels." (PMID 38997406, 2024). "We then investigated the impact of BC on EMT in lung cancer cells and found that the expression levels of Slug, N‐cadherin, Snai1 and ZEB1 were significantly elevated in BC‐overexpressing 95C, 95D, A549 or PC9 cells, whereas that of E‐cadherin was robustly reduced." (PMID 36650118, 2023). "Similarly, overexpression of miR-199a-3p significantly reduced tumor growth, cell proliferation, sphere formation capacity and ALDH expression of A549 lung carcinoma cells, due to down-regulation of ZEB1." (PMID 38139138, 2023). "Several independent research teams have successively confirmed that the ZEB1‐driven EMT process in lung cancer cells was accompanied by a decrease in the expression of the epithelial cell adhesion molecule E‐cadherin and EPCAM and an increase in the expression of the cytoskeletal protein vimentin." (PMID 36808651, 2023). "For instance, STK11 inactivation triggers EMT in lung cancer cells by inducing ZEB1 expression." (PMID 37506141, 2023).
lung carcinoma (continued). "Likewise, repression of miR200 and TBC1D2b in lung cancer cells by ZEB1 complex induces E-cadherin endocytosis and endosomal degradation." (PMID 38097578, 2023). "This is consistent with the reported significance of Zeb1 in lung cancer." (PMID 36604626, 2023). "Given that HORMAD1 increased the expression of ZEB-1, but not Snail1 or Slug, we hypothesized that HORMAD1 promotes EMT in lung cancer cells by increasing the expression of ZEB-1." (PMID 35347116, 2022). "Additionally, Manshouri and colleagues demonstrated that the ZEB1/NuRD complex inhibits TBC1D2b to stimulate E-cadherin internalization and promotes metastasis in lung cancer." (PMID 35884488, 2022). "BPL2 suppresses ZEB1 gene regulation in lung cancer cell lines and induces cell death." (PMID 36547923, 2022). "ZEB1 is a well-known transcription factor that is upregulated in various tumor cell lines and is related to the invasion and migration of cells in patients with lung cancer." (PMID 36547923, 2022). "Moreover, TCGA data mining and analysis show that Atg5 and Zeb1 are poor prognostic markers of lung cancer." (PMID 33468994, 2021). "Furthermore, a recent research announced that suppression of FBP1 transcription by ZEB1 is a critical oncogenic event in lung cancer progression." (PMID 33897890, 2021). "In agreement with the correlation analysis between β3 integrin and EMT markers, β3 integrin-overexpressing lung cancer cells showed increased mesenchymal markers, including N-cadherin, vimentin, and ZEB1; however, only small reductions were observed in E-cadherin, OVOL1, and ZO-1." (PMID 33883697, 2021). "Based on our clinical, in vitro, and in vivo studies, this study provided evidence that CD44 promotes lung cancer metastasis through ERK/ZEB1 activation and may serve as a potential therapeutic target for lung cancer metastasis." (PMID 34439211, 2021). "Moreover, The Cancer Genome Atlas (TCGA) data mining and analysis show that Atg5 and Zeb1 are poor prognostic markers of lung cancer." (PMID 33468994, 2021). "Finally, the lung cancer specimens from patients with acquired resistance to EGFR‐TKI showed increased expression of ZEB1, BMI1, and ALDH1A, than in specimens before treatment." (PMID 33764690, 2021). "ZEB1 has been reported to promote the metastatic ability of different cancers, including lung cancer, while Claudin-1 is a metastasis suppressor in lung cancer." (PMID 34439211, 2021). "Invariably, moderate and strong expression of ZEB1 was found in 60% of PHRF1 moderately expressed specimens (n = 32), and in 80% of PHRF1 strongly expressed specimens (n = 40), [respectively,?] indicating that PHRF1 and ZEB1 exhibited a positive correlation in lung cancer specimens." (PMID 32730336, 2020). "It has been reported that miR-641 can target MDM2 in lung cancer and serve as a tumor suppressor; miRNA-641 inhibits the growth, migration and invasiveness, prompts cervical cancer cell apoptosis via straightly targeting zeb1." (PMID 32667627, 2020). "Furthermore, Chen and colleagues have found that miR-200c/ZEB1 reciprocal axis-mediated CD8+ T cell immunosuppression promoted metastasis of lung cancer." (PMID 31534537, 2019). "In lung cancer, leptin is also known to induce EMT-associated morphological changes by decreasing expression of E-cadherin and keratin and increasing expression of the mesenchymal markers vimentin and ZEB1." (PMID 31200510, 2019). "Notably, down-regulation of ZEB1 resulted in significant inhibition of cisplatin-resistance in ovarian and lung cancers." (PMID 31497537, 2019). "ZEB1 is downregulated in four lung cancer and ILDs datasets, and overregulated in PAH." (PMID 31867044, 2019). "ZEB1 interacted with the FBP1 promoter to enhance DNA methylation in lung cancer cells." (PMID 30429463, 2018).
lung carcinoma (continued). "Indeed, there was a significant correlation between levels of AXIN2 and the EMT markers VIM (Vimentin) and ZEB1 (Zinc Finger E-Box Binding Homeobox 1), which again was lost in tumor samples from Metformin-taking lung cancer patients." (PMID 29977599, 2018). "The ZEB1/TLE1-mediated suppression of E-cadherin expression may represent a new pathway utilized by lung cancer cells to acquire anoikis resistance and anchorage-independent growth in vitro, and tumorigenicity in vivo." (PMID 29069783, 2017). "Hence, specific inhibition of the ZEB1/TLE1 nuclear pathway is a viable therapeutic strategy to circumvent lung cancer disease initiation and progression." (PMID 29069783, 2017). "In the case of TLE1-mediated E-cadherin repression in NSCLC cells, Zeb1, an EMT promoting factor uniquely correlated with the loss of E-cadherin expression in human lung cancer cell lines, may, in part, underlie TLE1 recruitment to the E-cadherin promoter." (PMID 27655370, 2016). "The role of ZEB1 in early-stage lung cancer remains poorly explored." (PMID 27456471, 2016). "ZEB1 expression level could also be a predictor to therapeutic responses such as resistance to epidermal growth factor receptor inhibitors for lung cancers." (PMID 25197668, 2014). "In lung cancer, ZEB1 appears to be a major factor in the EMT process." (PMID 24216980, 2013). "LKB1 inactivation triggers EMT in lung cancer cells through the induction of ZEB1." (PMID 23768087, 2013). "Furthermore, there were statistically significant differences in OS, PFS, and DMFS between patients with low and high expression of Snail, Twist1, and ZEB1, indicating that increased expression of Snail, Twist1, and ZEB1 was correlated with lung cancer progression and poor patient survival." (PMID 40259641, 2025). "In lung cancer cells, LPCAT3 transcription may be controlled by the transcription factor ZEB1 together with yes-associated protein (YAP), providing a possible rationale for the association between high ZEB1 levels and higher cellular ferroptosis sensitivity." (PMID 38908072, 2024). "In addition, the mRNA expression levels of CIB2 and ZEB1 were also upregulated in osimertinib-resistant lung cancer cell lines, which indicates that CIB2 and ZEB1 may contribute to osimertinib resistance." (PMID 39264588, 2024). "Also, a previous report indicates that ZEB1 induces EMT in lung cancer." (PMID 36774778, 2023). "The ZEB1/AGR2 double-negative feedback loop is associated with lung cancer invasion and metastasis." (PMID 35454770, 2022). "Considering that EMT have been reported to be highly associated with chemotherapeutic resistance in lung cancer, we moved to validate whether the EMT-inducing transcription factors (EMT-TFs) including ZEB1, SNAIL and TWIST were involved in Biochanin A-regulated chemosensitivity." (PMID 36512117, 2022). "Finally, we examined the expression of PHRF1 and ZEB1 in human lung cancer specimens." (PMID 32730336, 2020). "The four TFs (YY1, ZEB1, NR4A2 and E2F1) found coexpressed and identified with the DAVID-Opossum analysis have evidence of its association with tumorigenic processes, that could relate them to establishment of lung cancer." (PMID 31867044, 2019). "Therefore, ZEB1 downregulation in lung cancer could be related to its ability to inhibit tumor growth, which should be important to maintain in early stages of lung cancer." (PMID 31867044, 2019). "As ErbB3 is essential for growth of EGFR-mutated lung cancer cells, the ZEB1/miR-200 negative feedback loop might potentially provide a cell context-dependent regulation of ErbB3." (PMID 28587302, 2017). "Indeed, H3K27 acetylation was decreased in ZEB1-induced EMT in lung cancer cells." (PMID 26789630, 2016). "ZEB1 upregulation in lung cancer could be controlled by cyclooxygenase-2." (PMID 25197668, 2014).
lung carcinoma (continued). "Our scrutiny of 13 murine lung cancer cell lines and TCGA-LUAD data disclosed a positive correlation between ZEB1 and HAS2 mRNA levels, solidifying ZEB1’s role as a transcription activator for HAS2, an HA synthase." (PMID 40178908, 2025). "In human lung cancer cells, ITIH2 and ZEB1 mRNA levels were substantially higher in mesenchymal-like lung cancer cells (H1299) than in epithelial-like cells (HCC827)." (PMID 40178908, 2025). "Nuclear prothymosin α inhibits epithelial‐mesenchymal transition (EMT) in lung cancer by increasing Smad7 acetylation and competing with Smad2 for binding to SNAI1, TWIST1, and ZEB1 promoters." (PMID 40259641, 2025). "Previous studies have shown that QKI binds upstream and downstream of SMARCA5, ZEB1 and NDUFB2 RNA to promote circRNA formation in lung cancer, prostate cancer, and hepatocellular carcinoma." (PMID 40263288, 2025). "In lung cancer, cell lines with high Ankrd1 expression exhibited higher migration abilities, and Ankrd1 expression was regulated by the EMT marker ZEB1." (PMID 40362467, 2025). "Lung cancer cells undergoing EMT secrete increased levels of chemokines and transcription factors, such as the chemokine CCL2 and the transcription factor ZEB1, further enhancing the recruitment and polarization of TAMs." (PMID 40304000, 2025). "Research shows that ZEB1 can induce EMT in breast cancer, osteosarcoma, lung cancer, melanoma, and other epithelioma, leading to tumor metastasis and promoting drug resistance." (PMID 39409891, 2024). "The expression profiling of these proteins was consistent with the reported literature, which detected over-expression of ZEB1 and ZEB2 in human cancers, including lung cancer, prostate cancer, colorectal cancer, and bladder cancer." (PMID 38751602, 2024). "In EGFR-mutant lung cancer cell lines displaying EMT features, a downregulation of miR200c was observed, attributable to the increased level of ZEB-1 in these cells." (PMID 39766891, 2024). "ZEB1 contributes to immune evasion via reduction of CD8 T cells infiltration in cutaneous melanoma and lung cancer." (PMID 38191418, 2024). "ZEB1 is also downstream of RAS and BRAF in lung carcinomas and melanomas and mediates some of the signaling of oncogenic RAS in lung carcinomas." (PMID 37870961, 2023). "LINC00273 has been shown to facilitate lung cancer EMT via sponging miR-200a-3p and inducing zinc finger E-box binding homeobox 1 (ZEB1) expression." (PMID 36979471, 2023). "Only mature collagen fibers can induce EMT, as knockdown of the collagen cross-linking enzyme LOXL2, which is also regulated by ZEB1, abolishes FAK and Src activation and the metastasis of mouse lung cancer 344SQ cells in vitro and in vivo." (PMID 38139154, 2023). "In lung cancer patients, lower expression of ACE2 is responsible for up regulation of Zinc Finger E-Box Binding Homeobox 1 (ZEB1)." (PMID 37153428, 2023). "In EGFR-mutant lung cancer, EMT inhibits BIM through EMT-inducing transcription factors, ZEB1, and TWIST1, and becomes resistant to EGFR-TKIs19–21." (PMID 35790819, 2022). "ZEB1, TRAF4, and TGF-β1 are involved in lung cancer metastasis by EMT proteins while PD-L1, EGFR, TLR7 and TLR8 are involved in inhibiting the immune system." (PMID 36032679, 2022). "In the cisplatin-resistant lung cancer cell line A549/DDP, USP51 knockdown significantly induces apoptosis and the ubiquitin-mediated degradation of ZEB1, whereas overexpression of USP51 decreases the cleavage of PARP-1 and caspase-3." (PMID 35454770, 2022). "LncRNA H19 is also highly expressed in lung cancer, and by inhibiting the function of miR-200a, upregulates the expression of ZEB1 and ZEB2, promoting the epithelial-mesenchymal transition and enhancing lung cancer cell proliferation and metastasis." (PMID 36406130, 2022).